HASPIN (histone H3 associated protein kinase)
Diseases named in the same sentence as HASPIN in open-access papers:
HASPIN is named in the same sentence as 26 diseases in open-access papers, as found by Europe PMC text mining. Sharing a sentence is not in itself a finding about the gene and the disease. The quoted sentences say what the papers report.
breast carcinoma (9 papers, 2019 to 2026). "Chen and co-authors discovered that alisertib is more effective when HASPIN (histone H3-associated protein kinase) is inhibited through CRISPR/Cas9 in breast cancer." (PMID 40548119, 2025). "Sangivamycin inhibits cellular kinases that are overexpressed in some cancer cells — most notably protein kinase C and histone H3 associated protein kinase — leading to apoptosis in pancreatic cancer cells, breast cancer MCF-AR cells, and primary effusion lymphoma cells." (PMID 34807849, 2022). "Therefore, there is a possibility that HASPIN expression in breast cancer tissues is associated with the number of proliferating cells." (PMID 33852630, 2021). "In this study, we examined the in vitro and in vivo effects of the HASPIN inhibitor CHR-6494 on different breast cancer cell lines." (PMID 33852630, 2021). "A recent study revealed that in all four subtypes of breast cancer tissue, mRNA levels of HASPIN were significantly higher than in corresponding adjacent normal tissues, suggesting that HASPIN is a potential target for breast cancer therapy." (PMID 33852630, 2021). "We found that HASPIN was expressed in breast cancer cells of all molecular subtypes, as well as in immortalized mammary epithelial cells." (PMID 33852630, 2021). "A recent study has also demonstrated that among the four breast cancer subtypes, luminal A breast cancer tissues had the lowest HASPIN expression levels, whereas basal-like breast cancer tissues exhibited the highest HASPIN expression." (PMID 33852630, 2021). "Taken together, our findings imply that although HASPIN is required for breast cancer cell proliferation, its partial inhibition by chemical agents might not be sufficient to suppress tumor growth in vivo." (PMID 33852630, 2021). "To examine whether there is a correlation between the HASPIN expression level and growth rate of breast cancer cells, we next examined the growth rates of the breast cancer cell lines (left)." (PMID 33852630, 2021). "Although HASPIN appears to play an important role in cancer progression, its role in breast cancer development and progression remains largely unknown." (PMID 33852630, 2021). "To confirm the mRNA levels of HASPIN in different breast cancer types, we performed quantitative real-time PCR (qRT-PCR) analysis using several breast cancer cell lines and MCF10A cells, which are immortalized human mammary epithelial cells commonly used as a normal breast cell model." (PMID 33852630, 2021). "As HASPIN regulates cell cycle progression, HASPIN inhibition may block mitosis in breast cancer cells." (PMID 33852630, 2021). "Development of more potent and selective HASPIN inhibitors and new biotechnological applications such as CRISPR interference that allow suppression of genetic transcription would be valuable in the treatment of breast cancer patients." (PMID 33852630, 2021). "As HASPIN mRNA levels are elevated in human breast cancer tissues compared with adjacent normal tissues, we examined the growth-suppressive effects of CHR-6494, a potent HASPIN inhibitor, in breast cancer cell lines in vitro and in vivo." (PMID 33852630, 2021). "HASPIN expression levels appeared to be correlated with the cell growth rate but not the molecular subtype of breast cancer." (PMID 33852630, 2021). "Furthermore, it is possible that the administered dose of CHR-6494 (50 mg/kg) was not sufficient to inhibit HASPIN function, especially considering that the IC50 values of CHR-6494 are higher in breast cancer cell lines than in other cancer cell lines, such as HCT-116 and HeLa cells." (PMID 33852630, 2021).
pancreatic cancer (4 papers, 2021 to 2025). "RNA interference-mediated knockdown of HASPIN has been shown to inhibit cell proliferation and cause cell cycle arrest at the G2/M phase, thereby inducing apoptosis of pancreatic cancer cells." (PMID 33852630, 2021). "Previous reports have shown that HASPIN inhibitors have antiproliferative activity and induce apoptosis of melanoma, colon carcinoma, and pancreatic cancer cells." (PMID 33852630, 2021).
colorectal cancer (3 papers, 2020 to 2025). A primary or metastatic malignant neoplasm that affects the colon or rectum. "Therefore, the development of HASPIN inhibitors, such as coumestrol, will be useful in preventing colorectal cancer and in suppressing the risk of recurrence after surgical treatment." (PMID 39336163, 2024). "Our results suggest that HASPIN inhibitors may be useful as anti-cancer agents and for the treatment of hypogonadism in colorectal cancer patients." (PMID 31833958, 2020).
lung carcinoma (3 papers, 2019 to 2023). "Through transcriptomeanalysis of lung cancer patients, PLK1 was determined as a druggablesynergistic partner to complement HASPIN inhibition." (PMID 37396870, 2023). "Therefore, LJ4827 is a novel anticancer therapeuticfor selectively impeding cancer mitosis through potent HASPIN inhibition,and simultaneous HASPIN and PLK1 interference is a promising therapeuticstrategy for lung cancer." (PMID 37396870, 2023).
Alzheimer disease (2 papers, 2023 to 2025). A progressive, neurodegenerative disease characterized by loss of function and death of nerve cells in several areas of the brain leading to loss of cognitive function such as memory and language. "Oral administration of soybean sprouts grown for increased coumestrol (a HASPIN inhibitor) decreased the phosphorylated tau protein level in the hippocampus and suppressed short-term memory loss in the Alzheimer’s disease model mice (5xFAD)." (PMID 36829593, 2023). "In this paper, we showed that HASPIN is expressed in the hippocampus and phosphorylates tau protein and that soybean sprouts containing a HASPIN inhibitor suppress the onset of Alzheimer’s disease." (PMID 36829593, 2023). "Next, we examined the expression of HASPIN in Alzheimer’s disease model mice, which are transgenic mice expressing transgenes with five familial Alzheimer’s disease mutations (5xFAD) in the amyloid precursor protein and Presenilin1." (PMID 36829593, 2023). "In this study, we identify that the tau protein is involved as a phosphorylation substrate of HASPIN, and examine the effects of HASPIN inhibition on Alzheimer’s disease in vivo and in vitro." (PMID 36829593, 2023). "Moreover, we found that the oral administration of coumestrol, a natural HASPIN inhibitor, suppressed Alzheimer’s disease onset in 5XFAD mice, a model of the disease, and elevated serum testosterone levels in both these mice and wild-type controls." (PMID 40906146, 2025). "HASPIN may be involved in Alzheimer’s, so soybean sprouts containing HASPIN inhibitors are considered to be very promising ingredients for the prevention of Alzheimer’s disease." (PMID 36829593, 2023). "Functional analysis of HASPIN may help treatment of Alzheimer’s disease." (PMID 36829593, 2023). "To examine whether HASPIN is involved in the onset of Alzheimer’s disease through tau protein phosphorylation, we investigated the effects of a diet including soybean sprouts rich in the HASPIN inhibitor coumestrol in a mouse model of Alzheimer’s disease (5xFAD)." (PMID 36829593, 2023).
gallbladder carcinoma (2 papers, 2021 to 2024). "More recently, HASPIN upregulation has been reported during gallbladder carcinoma (GBC) progression, and HASPIN silencing by shRNA inhibited proliferation of GBC cells." (PMID 33852630, 2021).
hypogonadism (2 papers, 2020 to 2024). A disorder characterized by decreased function of the gonads. "In this study, the ingestion of bean sprouts containing large amounts of the HASPIN inhibitor, coumestrol, suppressed the progression of intestinal polyp development, cachexia, and hypogonadism, and increased serum testosterone in mice." (PMID 39336163, 2024). "As administration of CHR-6494 suppressed the development of polyps and hypogonadism in ApcMin/+ mice, HASPIN may not only function in chromosome segregation but also participate in the Wnt/β-catenin signaling pathway." (PMID 39336163, 2024). "In conclusion, although our results arise from a small sample, they indicate that HASPIN inhibitors may be useful as anti-cancer agents and for the treatment of hypogonadism in CRC." (PMID 31833958, 2020).
melanoma (2 papers, 2020 to 2021). A malignant, usually aggressive tumor composed of atypical, neoplastic melanocytes. "CX-6258, an orally administered pan-Pim kinase inhibitor, has recently been shown to inhibit HASPIN and reduce proliferation of melanoma cell lines (A375-S and A375-RMR) both in vitro and in vivo." (PMID 33852630, 2021). "Similarly, CHR-6494, a potent HASPIN inhibitor, has been demonstrated to inhibit proliferation of the triple-negative breast cancer cell line MDA-MB-231 and various melanoma cell lines in vitro." (PMID 33852630, 2021).
prostate carcinoma (2 papers, 2024). A carcinoma that arises from epithelial cells of the prostate gland. "Although it has been reported that HASPIN inhibitors, including coumestrol, suppress the growth of prostate cancer and hormone-dependent breast cancer cells, the ingestion of bean sprouts increased serum testosterone levels in male mice." (PMID 39336163, 2024).
Familial adenomatous polyposis (1 paper, 2024). Familial adenomatous polyposis (FAP) is characterized by the development of hundreds to thousands of adenomas in the rectum and colon during the second decade of life. "Intraperitoneal administration of the artificial HASPIN inhibitor CHR-6494 was shown to suppress colon cancer in a mouse model of familial adenomatous polyposis (ApcMin/+)." (PMID 39336163, 2024). "In this study, the antitumor effect of ingesting bean sprouts containing the HASPIN inhibitor coumestrol was investigated using a mouse model of familial adenomatous polyposis (ApcMin/+)." (PMID 39336163, 2024).
polyp (1 paper, 2020). A usually exophytic mass attached to the underlying tissue by a broad base or a thin stalk. "Thus, HASPIN’s function, which is required for cell growth, was not complemented by other molecules in Apcmin/+ mice treated with CHR-6494, and intestinal polyp development was suppressed." (PMID 31833958, 2020).
cancer (18 papers, 2017 to 2025). A tumor composed of atypical neoplastic, often pleomorphic cells that invade other tissues. "We confirm synthetic lethal relationships between DDX11 and the tumor suppressor cohesin subunit STAG2, which is frequently mutated in several cancer types and the kinase HASPIN." (PMID 38478595, 2024). "The expression levels of HASPIN in various cancers are associated with tumor malignancy and poor survival, suggesting that HASPIN inhibition may suppress cancer growth." (PMID 33852630, 2021). "The KINOME project identified numerous protein kinase inhibitors, including HASPIN inhibitors, and the inhibition of HASPIN has been shown to suppress the proliferation of cancer cells." (PMID 40906146, 2025). "Coumestrol, a natural compound found in bean sprouts, has been reported to inhibit HASPIN kinase activity and suppress cancer cell proliferation." (PMID 40906146, 2025). "It has recently been reported that HASPIN inhibitors specifically inhibit the proliferation of various cancer cells." (PMID 39336163, 2024). "The HASPIN inhibitory effect (ID50 50 μM) of coumestrol was sufficient to suppress cancer, although the ID50 was nearly 1000-fold lower than that of CHR6494 (approximately 50 nM) in suppressing the proliferation of cultured cancer cells." (PMID 39336163, 2024). "On the other hand, inhibitors of HASPIN have been identified and shown to specifically suppress the proliferation of various cancer cells." (PMID 36829593, 2023). "Inhibition of HASPIN function is a major target for suppressing cancer cells, as cancer cell growth was also suppressed in RNA interference (RNAi) experiments against HASPIN." (PMID 36829593, 2023). "LJ4827’sHASPIN inhibition revealed a clear antimitotic effect on cancer celllines with high HASPIN expression by interfering with Aurora B recruitmentat the mitotic centromere, which would not occur in normal cells." (PMID 37396870, 2023). "In order to proceed with a detailed analysis of the function of HASPIN in normal cells, in contrast to abnormal cells such as cancer cells, we attempted to identify proteins that bind to HASPIN from the mouse testis cDNA library, using a two-hybrid system." (PMID 36012324, 2022). "Recent advances in kinome projects have led to the isolation of HASPIN kinase inhibitors, and studies have reported that inhibitors of HASPIN kinase activity suppress the proliferation of cancer cells." (PMID 36012324, 2022). "In somatic cells, it has been shown that HASPIN functions in cancer cells and that HASPIN inhibitors suppress the growth of cancer cells." (PMID 36012324, 2022). "Further analysis of the relationships between molecules that interact with HASPIN will deepen our understanding of spermatogenesis, cell division, and cancer cell proliferation." (PMID 36012324, 2022). "Of note, HASPIN was found to be upregulated in a wide range of cancers, and high HASPIN expression levels in tumors have been associated with a poor patient prognosis." (PMID 33852630, 2021). "Recently, experiments using HASPIN inhibitors have shown that the proliferation of cultured cancer cells was specifically suppressed, as was intestinal polyp development in Apcmin/+ mice in a familial colon tumor disease model in vivo." (PMID 34262392, 2021). "Recently, HASPIN inhibitors have been shown to inhibit cancer cell growth, suggesting that HASPIN’s function is not complemented during cell division in actively proliferating cells." (PMID 31833958, 2020). "No major side effects have been reported in HASPIN-deficient mice, or in preclinical studies of HASPIN inhibitors, suggesting that small-molecule compounds targeting HASPIN may be promising candidates for cancer therapy." (PMID 40906146, 2025).
cancer (continued). "Several HASPIN inhibitors have since been characterized, and their antiproliferative effects against a wide range of human cancer cell types have been reported, including colon, breast, prostate, skin, pancreas, lung, ovary, bladder, biliary tract, and hematopoietic system cancers." (PMID 40906146, 2025). "HASPIN inhibitors suppress the proliferation of various cancer cells." (PMID 39336163, 2024). "Several HASPIN inhibitors suppress cancer cell proliferation." (PMID 39336163, 2024). "Therefore, the HASPIN inhibitor coumestrol, within bean sprouts, is considered to have been the main factor involved in suppressing cancer." (PMID 39336163, 2024). "HASPIN inhibitors, such as coumestrol, may be useful as cancer treatment drugs that restore fertility in such patients." (PMID 39336163, 2024). "In this study, Western blotting of the small intestine with polyps revealed the expression of HASPIN, indicating that HASPIN may be a useful cancer marker." (PMID 39336163, 2024). "It has been reported that HASPIN inhibitors suppress the proliferation of various cancer cells." (PMID 39336163, 2024). "The phosphorylation-induced activation of C1QBP by HASPIN in cancer cells may be involved in the growth of cancer cells." (PMID 36012324, 2022). "Given that HASPIN expression is restricted to proliferating cells, HASPIN inhibition could be a viable strategy for cancer treatment." (PMID 33852630, 2021). "Analysis of intronless genes, including HASPIN, may be useful in researching both infertility and cancer treatments." (PMID 34262392, 2021). "In this study, we observed polyp formation in ApcMin/+ mice following administration of HASPIN inhibitor CHR-6494 to determine whether it can prevent cancer growth in vivo." (PMID 31833958, 2020). "To investigate whether HASPIN inhibitor CHR-6494 can suppress cancer cell growth in vivo, we administered CHR-6494 to ApcMin/+ mice, a model of human CRC." (PMID 31833958, 2020). "In this study, we examined whether HASPIN inhibitor CHR-6494 suppresses cancer progression in ApcMin/+ mice, a familial colon tumor disease model." (PMID 31833958, 2020). "Inhibitors of HASPIN kinase activity have also been reported to suppress cancer growth." (PMID 31833958, 2020). "Experiments using cultured cells and haspin-disrupted mice have indicated that HASPIN functions may be compensated by other molecules in normal cells; however, HASPIN may play an important role in cell division during the proliferation of male germ cells and cancer cells." (PMID 31833958, 2020). "Previous studies have shown that HASPIN is broadly and highly expressed in various cancers compared with the corresponding non-malignant tissues." (PMID 33852630, 2021).
tumor (11 papers, 2012 to 2025). "Haspin kinase (HASPIN) is related to the regulation of STING signaling; therefore, HASPIN inhibition reduces proliferation of the tumor cells by the activation of the STING pathway and STING-dependent type I IFN and decreased Treg." (PMID 34830754, 2021). "ZWINT, HASPIN, and CDCA3 are all expressed in tumor cells to promote proliferation." (PMID 40416783, 2025).
infection (1 paper, 2025). The state of being infected such as from the introduction of a foreign agent such as serum, vaccine, antigenic substance or organism. "The kinase-substrate phosphomotif pattern analysis revealed several kinases, including EEF2K, HASPIN, MAPK9, MAST2, and Spleen tyrosine kinase (SYK), that can phosphorylate multiple NiV proteins at various sites, suggesting regulatory roles during infection." (PMID 41424949, 2025).
HASPIN also shares sentences with these, for which no sentence is quoted: colon carcinoma (3 papers); epithelial ovarian cancer (2); intestinal polyp (2); ovarian cancer (2); skin melanoma (2); bladder cancer (1); dementia with Lewy bodies (1); familial Alzheimer disease (1); lung adenocarcinoma (1); primary effusion lymphoma (1); thyroid (1); thyroid cancer (1).